LINS1 (lines homolog 1)
Synonyms: LINS; WINS1; MRT27
Tractability: PROTAC: ubiquitination databases record sites on it.
Gene: Protein-coding gene on chromosome 15 (100,559,369 to 100,603,230, reverse strand). Ensembl gene ENSG00000140471.
Subcellular location (Human Protein Atlas): Nucleoplasm
Gene Ontology:
Biological process: cognition
Genetic constraint (gnomAD): Loss-of-function variants: 23 observed, 37.59 expected, observed/expected ratio (o/e) 0.61, 90% interval 0.44 to 0.87. The upper end of that interval is the gene's LOEUF score, 0.87, which puts it in group 3 of 6, group 1 being the genes least tolerant of losing a copy. Missense variants: 935 observed, 896.9 expected, observed/expected ratio (o/e) 1.04, 90% interval 0.99 to 1.1. Synonymous variants: 331 observed, 320.01 expected, observed/expected ratio (o/e) 1.03, 90% interval 0.94 to 1.13.
Gene-disease validity (ClinGen):
ClinGen rates the evidence that LINS1 causes each of these diseases.
complex neurodevelopmental disorder (autosomal recessive): Definitive. A disorder that involves more than one phenotype associated with the central nervous system, including but not limited to intellectual disability, autism, and seizures (epilepsy).
Homologues: Orthologues: chimpanzee LINS1 (99% identical), macaque LINS1 (94% identical), pig LINS1 (76% identical), dog LINS1 (73% identical), guinea pig LINS1 (62% identical), mouse Lins1 (59% identical), rat Lins1 (57% identical), rabbit LINS1 (52% identical), tropical clawed frog lins1 (33% identical), zebrafish lins1 (26% identical), Drosophila melanogaster lin (14% identical).
Diseases named in the same sentence as LINS1 in open-access papers:
LINS1 is named in the same sentence as 9 diseases in open-access papers, as found by Europe PMC text mining. Sharing a sentence is not in itself a finding about the gene and the disease. The quoted sentences say what the papers report.
Ataxia (1 paper, 2020). Ataxia refers to impaired coordination of voluntary muscle movement. "In order to check the polymorphic nature of the LINS1 mutation, we checked whole exome sequencing data of >70 patients with ID, ataxia, Parkinson's disease and healthy unaffected relatives and we did not observe this mutation." (PMID 32499722, 2020).
Intellectual disability (1 paper, 2020). "LINS1 has been reported to cause MRT27 (mental retardation, autosomal recessive 27), a rare autosomal recessive nonsyndromic intellectual disability, with limited characterization of the phenotype." (PMID 32499722, 2020).
mental retardation, autosomal recessive 27 (1 paper, 2020). "LINS1 has previously been identified as a genetic cause for MRT27 (mental retardation, autosomal recessive 27) which has been reported in a small number of patients with limited characterization of their phenotypic features." (PMID 32499722, 2020).
prostate carcinoma (1 paper, 2024). A carcinoma that arises from epithelial cells of the prostate gland. "We also provide evidence that the mammalian homologs of Hyd (UBR5), Lin (LINS1), and Bowl (OSR1/2) constitute an analogous protein degradation pathway in human cells, and that OSR2 promotes prostate cancer tumorigenesis." (PMID 39137945, 2024). "We also provide evidence that the mammalian homologs of Hyd (UBR5, known to be recurrently dysregulated in various human cancers), Lin (LINS1), and Bowl (OSR1/2) constitute an analogous protein degradation pathway in human cells, and that OSR2 promotes prostate cancer tumorigenesis." (PMID 39137945, 2024).
Vestibular schwannoma (1 paper, 2023). A vestibular schwannoma (also known as acoustic neuroma, acoustic neurinoma, or acoustic neurilemoma) is a benign, usually slow-growing tumor that develops from the VIIIth cranial nerve supplying the inner ear. "Protein lines homolog 1 (LINS1) that was also present in all CS samples is a regulator of the wingless/Wnt pathway whose inhibition decrease vestibular schwannoma growth." (PMID 37627098, 2023).
LINS1 also shares sentences with these, for which no sentence is quoted: infection (1 paper); microcephaly (1); Parkinson disease (1); tumor (1).